GAS5 (growth arrest specific 5)
Diseases named in the same sentence as GAS5 in open-access papers (continued):
Sharing a sentence is not in itself a finding about the gene and the disease.
bladder cancer (33 papers, 2013 to 2025). "A study investigating the interplay between GAS5 and miR-21 in bladder cancer cell reversal mechanisms showed that low GAS5 levels and high miR-21 levels were associated with bladder cancer." (PMID 39114567, 2024). "Most studies have indicated that lincRNAs and snoRNAs are upregulated in bladder cancer and associated with oncogenesis, progression and metastasis, although GAS-5, MEG3 and linc00641 were shown to be tumour suppressor genes and were downregulated in BLCA." (PMID 36831352, 2023). "Another report on bladder cancer indicated that patients in Iranian populations with the TG haplotype carriers of GAS5 (rs2067079 and rs6790) have a high risk of bladder cancer." (PMID 32354045, 2020). "Individuals with the TG genotypes of GAS5 rs2067079 and rs6790 are at a significantly increased risk of bladder cancer compared with those with the wild-type genotype in Iranian populations." (PMID 32354045, 2020). "In bladder cancer, lncRNA GAS5 associates with CDK6 and reduces both CDK6 mRNA and protein levels, resulting in the inhibition of cell proliferation." (PMID 25959498, 2015). "Gain-of-function and loss-of-function studies showed that GAS5 inhibits bladder cancer cell proliferation, at least in part, by regulating CDK6 expression." (PMID 24069260, 2013). "Gain-of-function and loss-of-function studies confirmed that GAS5 regulates cell cycle and inhibits bladder cancer cell proliferation, partly by regulating CDK6 expression." (PMID 24069260, 2013). "High expression of HOTAIR and GAS5 was shown to be associated with poor survival in bladder cancer." (PMID 36685879, 2022). "This suggested that low GAS5 and high miR‐21 could be used to predict more severe bladder cancer and worse prognosis, and that high GAS5 level might be associated with low expression of miR‐21." (PMID 32069387, 2020). "In summary, high levels of GAS5 and low levels of miR‐21 might be associated with higher survival rate in bladder cancer." (PMID 32069387, 2020). "High levels of GAS5 and low levels of miR‐21 might be associated with a higher survival rate in bladder cancer patients." (PMID 32069387, 2020). "In bladder cancer, the expression level of growth arrest‐specific transcript 5 (GAS5) was decreased and the expression level of miR‐21 was elevated, and high levels of GAS5 and low levels of miR‐21 might be associated with higher survival." (PMID 32069387, 2020). "Overall, GAS5 exerts anti-proliferative and pro-apoptotic effects on bladder cancer cells by modulating the miR-21/PTEN pathway." (PMID 39114567, 2024). "Recent studies have revealed that GAS5 is downregulated in bladder cancer, leading to increased cell proliferation through CDK6 regulation." (PMID 39114567, 2024). "Irregular expression of HOTAIR, UBC1, H19, and GAS5 has been reported to be related to overall survival in bladder cancer however, more confirmative studies are needed to make a definite conclusion." (PMID 36685879, 2022). "Not only that, a large number of studies suggested that GAS5 inhibits tumor progression in other cancers, including cervical cancer 30, liver cancer 31 and bladder cancer." (PMID 33391419, 2021). "It has been found that the expression of lncRNA GAS5 is decreased in bladder cancer specimens, and overexpression of lncRNA GAS5 prevents the proliferation and migration of bladder cancer cells." (PMID 34026626, 2021). "GAS5 inhibited bladder cancer cells proliferation and promoted apoptosis, and miR‐21 had the opposite effects." (PMID 32069387, 2020). "The aim of this study was to investigate the mechanism by which growth arrest‐specific transcript 5 (GAS5) regulates bladder cancer cells." (PMID 32069387, 2020). "To investigate the mechanism by which GAS5 regulates proliferation and apoptosis through miR‐21 in bladder cancer cells, we conducted further studies." (PMID 32069387, 2020).
bladder cancer (continued). "Through further cell experiments, we also found that low expression of GAS5 promoted proliferation and inhibited apoptosis of bladder cancer cells." (PMID 32069387, 2020). "Cellular assay results also showed that in bladder cancer cells, GAS5 levels were low and miR‐21 levels were high." (PMID 32069387, 2020). "Survival analysis showed a higher survival rate in bladder cancer patients with high GAS5 expression and low miR‐21 expression." (PMID 32069387, 2020). "Correlation analysis showed that the levels of GAS5 and miR‐21 in bladder cancer tissues were inversely related (P = .0326)." (PMID 32069387, 2020). "In 35 bladder cancer patients, 18 cases had high expression of GAS5, whereas 17 had low expression of miR‐21." (PMID 32069387, 2020). "The results showed that in tumor tissues of patients with bladder cancer, GAS5 was generally lowly expressed but miR‐21 was highly expressed, and the two were negatively correlated to each other." (PMID 32069387, 2020). "In order to study the effect of GAS5 on bladder cancer cells, GAS5 overexpression (GAS5 group) and low expression (GAS5 siRNA group) of HTB‐9 cells were constructed, and transfection efficiency was detected by qRT‐PCR." (PMID 32069387, 2020). "In the case of prostate and bladder cancers, two reports highlighted the connection of GAS5 with miRNAs." (PMID 33076450, 2020). "Functionally, overexpression of GAS5 reduced cell viability and induced cell apoptosis in T24 and EJ bladder cancer cells." (PMID 29445179, 2018). "Aberrant expression of long noncoding RNA GAS5 in bladder cancer (BC) cells was identified in recent studies." (PMID 29445179, 2018). "In the present study, we identify that the GAS5 expression is commonly downregulated in most bladder cancer specimens and in bladder cancer cell lines." (PMID 24069260, 2013). "Knockdown of GAS5 induces a significant decrease in G0/G1 phase and promotes bladder cancer cell proliferation, at least in part, by regulating CDK6 expression." (PMID 24069260, 2013). "In the present study, we found that the GAS5 expression is commonly downregulated in bladder cancer cell lines and human specimens." (PMID 24069260, 2013). "We then investigated the possible mechanisms that GAS5 regulates the bladder cancer cell proliferation." (PMID 24069260, 2013). "Knockdown of GAS5 promotes bladder cancer cell proliferation, whereas forced expression of GAS5 suppresses cell proliferation." (PMID 24069260, 2013). "GAS5 inhibition contributes to bladder cancer cell proliferation, whereas overexpression of GAS5 inhibits cell proliferation." (PMID 24069260, 2013). "We therefore thought that the role of GAS5 in regulating bladder cancer cell proliferation is mediated by modulating CDK6 expression." (PMID 24069260, 2013). "Similarly, GAS5 has been demonstrated as a tumor suppressor role in bladder cancer via inhibiting EZH2 expression and augmenting apoptosis." (PMID 36685879, 2022). "Additionally, overexpression of lncRNA GAS5 impairs the proliferation and migration of bladder cancer cells, and also promoted apoptosis in bladder cancer cells." (PMID 35526240, 2022). "Another lncRNA GAS5 was found to be decreased in bladder cancer." (PMID 36685879, 2022). "Furthermore, GAS5 has been reported to promote apoptosis by suppressing EZH2 transcription via the recruitment of transcription factor E2F4 to EZH2 promoter in bladder cancer cells." (PMID 36685879, 2022). "However, several studies have demonstrated that the downregulation of GAS5 is potentiating tumor progression in various cancers including bladder cancer." (PMID 36685879, 2022). "Few studies were conducted on the regulation of bladder cancer by GAS5 and miR‐21." (PMID 32069387, 2020). "GAS5 could exert antiproliferative and proapoptotic effects on bladder cancer cells through miR‐21 and PTEN." (PMID 32069387, 2020).
bladder cancer (continued). "Therefore, this study mainly analyzed the relation between GAS5 and miR‐21 and prognosis in bladder cancer as well as their roles in cell cytolergy of bladder cancer cells and the related mechanisms." (PMID 32069387, 2020). "This indicated that GAS5 might participate in the proliferation and apoptosis of bladder cancer cells by regulating miR‐21 and apoptosis‐related proteins and cell cycle‐associated proteins." (PMID 32069387, 2020). "GAS5 could inhibit the proliferation of bladder cancer cells and promote apoptosis by regulating PTEN through miR‐21." (PMID 32069387, 2020). "Moreover, lncRNA GAS5 was reported to suppress enhancer of zeste homolog 2 (EZH2) transcription via recruiting E2F4 to EZH2 promoter to induce bladder cancer cell apoptosis." (PMID 32308561, 2020). "It was also confirmed by miR and a prediction and dual‐luciferase reporter experiments that miR‐21 was a target of GAS5 in bladder cancer cells, and that GAS5 might regulate miR‐21." (PMID 32069387, 2020). "Similarly, gambogic acid induced GAS5 expression can produce pro-apoptotic effects in bladder cancer cells." (PMID 31784542, 2019). "GAS5 down-regulated in bladder cancer tissues could suppress the proliferation of bladder cancer cells and enhance cancer cell apoptosis." (PMID 30042171, 2018). "Based on these findings, we tested whether GAS5 regulates cell cycle and cell proliferation in bladder cancer cell." (PMID 24069260, 2013). "We found that GAS5 expression is significantly decreased in bladder cancer tissues." (PMID 24069260, 2013). "Based on these findings, we speculated whether expression of the GAS5 is abnormal and dysregulated GAS5 regulates cell proliferation in bladder cancer." (PMID 24069260, 2013). "Furthermore, overexpression of GAS5 remarkably inhibits CDK6 expression in bladder cancer cell lines." (PMID 24069260, 2013). "Altogether, these studies suggest that GAS5 could use for bladder cancer patient’s treatment." (PMID 36685879, 2022). "Therefore, downregulation of GAS5 increases CDK6 expression in bladder cancer cells." (PMID 24069260, 2013). "However, little is known about whether lncRNA-GAS5 (growth arrest-specific 5) regulates bladder cancer progression." (PMID 24069260, 2013). "Urinary exosomes from 42 bladder cancer patients were collected and quantified for seven lncRNAs (UCA1, H19, MALAT1, TUG1, GAS5, RMRP, and LINC01517), showing increased expression of RMRP, UCA1, and MALAT1 in bladder cancer patients." (PMID 40075875, 2025). "Besides, GAS5 may inhibit bladder cancer cell proliferation by suppressing the expression of CCL1." (PMID 34893045, 2021). "Most notably, upregulated lncRNA GAS5 has been demonstrated to inhibit the transcription of EZH2 via recruitment of E2F4 to EZH2 promoter and induced cell apoptosis of bladder cancer." (PMID 32308561, 2020). "So far, numerous studies have showed that lncRNAs are involved in bladder cancer development and progression, such as PVT1, ZEB2NAT, MDC1-AS and growth arrest-specific 5 (GAS5)." (PMID 30042171, 2018). "Taken together, our findings demonstrated a tumor-suppressor role of GAS5 by inhibiting EZH2 on transcriptional level, and additionally provided a novel therapeutic strategy for treating human bladder cancer." (PMID 29445179, 2018). "We further demonstrated that knockdown of GAS5 increases CDK6 mRNA and protein levels in bladder cancer cells." (PMID 24069260, 2013). "Additionally, genetic studies have demonstrated that GAS5 suppresses cell division protein kinase 6 (CDK6), thereby inhibiting bladder cancer progression." (PMID 36685879, 2022). "More specifically, GAS5 has the potential to inhibit EZH2 transcription by directly interacting with E2F transcription factor 4 (E2F4) and recruiting E2F4 to the promoter of EZH2 in bladder cancer cells." (PMID 34781960, 2021).
bladder cancer (continued). "The inhibition of miR‐21 reversed the effect of GAS5 on miR‐21 and PTEN, suggesting that GAS5 might regulate PTEN to participate in the proliferation and apoptosis of bladder cancer cells through miR‐21." (PMID 32069387, 2020). "Knockdown of GAS5 significantly increases CDK6 mRNA and protein levels in bladder cancer cell lines, but downregulation of GAS5 don’t change CDK2 and CDK4 expression level (data not shown)." (PMID 24069260, 2013). "Downregulated GAS5 increases bladder cancer cell proliferation, and a significant negative correlation is observed between the GAS5 and the CDK6." (PMID 24069260, 2013). "In order to investigate whether GAS5 regulates bladder tumorigenesis, we first examined the GAS5 expression level in bladder cancer tissues and adjacent normal tissues." (PMID 24069260, 2013). "Downregulated GAS5 promotes bladder cancer cell proliferation, partly by regulating CDK6, and thus may be helpful in the development of effective treatment strategies against bladder cancer." (PMID 24069260, 2013). "Moreover, GAS5 could exert antiproliferative and proapoptotic effects on bladder cancer cells through miR‐21 and PTEN, which provided new approaches for the treatment of bladder cancer." (PMID 32069387, 2020).
melanoma (33 papers, 2013 to 2025). A malignant, usually aggressive tumor composed of atypical, neoplastic melanocytes. "Initially, lncRNA GAS5 was found to be expressed at a poor level in melanoma tissues and cell lines and its deficiency attenuated the oxidative stress and apoptosis of melanoma cells." (PMID 32308561, 2020). "In such a way, reduced GAS5 expression is linked to progression of melanoma." (PMID 34725562, 2021). "Based on this above discussion, we hypothesized that lncRNA GAS5 acts as a suppressor in melanoma and its underlying mechanism could involve EZH2 and CDKN1C." (PMID 32308561, 2020). "For instance, overexpression of lncRNA GAS5 via lentiviral vectors has been shown to inhibit migration and invasion in melanoma cells by downregulating MMP2 expression and activity." (PMID 40282449, 2025). "Clinical samples of melanoma have consistently shown that GAS5 is downregulated in advanced disease, correlating with greater tumour thickness, ulceration, and nodal metastasis." (PMID 41463281, 2025). "GAS5 suppresses the ability of melanoma cells to migrate and invade via inhibition of MMP2 expression and its activity." (PMID 41463281, 2025). "GAS5 promotes apoptosis in melanoma; GAS5 knockdown induces G1/S progression and inhibits apoptosis by upregulating Bcl‐2, whereas GAS5 overexpression decreases Bcl‐2." (PMID 41463281, 2025). "Functionally, knocking down GAS5 in melanoma cells accelerates G1/S progression through increases in cyclin D1, CDK4, and p27; boosts viability; and blunts apoptosis via increased expression of Bcl-2." (PMID 41463281, 2025). "The authors reported that treatment of melanoma cells with decitabine, a demethylating agent, reverses GAS5 methylation and reduces cancer invasion." (PMID 41463281, 2025). "In malignant melanoma, knockdown of the lncRNA growth arrest-specific 5 (GAS5) led to increased intracellular ROS accumulation by elevating superoxide anion levels and promoting NADPH oxidase 4 (NOX4)-mediated GSH oxidation." (PMID 39595619, 2024). "For example, knockdown of the lcnRNA growth arrest-specific transcript 5 (GAS5) increases the levels of superoxide anion and oxidized glutathiones by altering the redox balance in melanoma cells." (PMID 34725562, 2021). "For instance, by mediating MMP2 expression andactivity in melanoma cells, long non-coding RNA (lncRNA) GAS5 represses theinvasion of cancer cells." (PMID 34837683, 2021). "GAS5 has been reported to enhance oxidative stress in melanoma cells, macrophages, and rats with cerebral ischemic stroke." (PMID 34616299, 2021). "Lastly, lncRNAs can also act as tumour suppressors in melanoma, however only growth arrest-specific transcript 5 (GAS5) and maternally expressed gene 3 (MEG3) have been reported so far." (PMID 33203119, 2020). "A375 cells were transduced with oe-G-NC and oe-GAS5 plasmids and melanoma cell-related biological changes were thus observed." (PMID 32308561, 2020). "Administration of GAS5, a tumour suppressor lncRNA, to nude mice inhibited melanoma growth, however further studies focused on the therapeutic value of GAS5 are needed." (PMID 33203119, 2020). "In another study, it was reported that knockdown of lncRNA GAS5 was observed to inhibit apoptosis as well as oxidative stress of melanoma cells and contribute to tumor progression in melanoma patients." (PMID 32308561, 2020). "In melanoma cell lines, lncRNA GAS5 expression was overexpressed or knocked down to clarify its effects on cell viability, apoptosis, and oxidative stress." (PMID 32308561, 2020). "The expression of lncRNA GAS5 in the cultured 4 melanoma cell lines (A375, SK-MEL-1, SK-MEL-2, and OCM-1) and human normal skin melanocyte cell line (PIG1) was assayed using RT-qPCR." (PMID 32308561, 2020). "A375 cells with lncRNA GAS5 silencing were added with DMSO or UNC1999 and the biological changes associated with melanoma cells were investigated by inhibiting the EZH2 expression and H3K27 methylation." (PMID 32308561, 2020).